SDC4 (syndecan 4)
Diseases named in the same sentence as SDC4 in open-access papers (continued):
Sharing a sentence is not in itself a finding about the gene and the disease.
inflammation (1 paper, 2023). Aberrant reaction of the microcirculation characterized by movement of fluid and leukocytes from the blood into extravascular tissues. "Here, we investigated the potential of syndecan-4 as a blood biomarker of cardiac inflammation." (PMID 37189684, 2023). "Thus, we conclude that syndecan-4 had limited clinical value as a circulating biomarker of cardiac inflammation and that immunomodulating therapies targeting IL-1β likely will affect the molecular processes that shed syndecan-4 ectodomains play locally in cardiac tissue." (PMID 37189684, 2023).
neurodegenerative disease (1 paper, 2017). A disorder of the central nervous system characterized by gradual and progressive loss of neural tissue and neurologic function. "Therefore, our results support Thy-1 and β3 Integrin/Syndecan-4 as potential targets for the clinical management of neurodegenerative diseases involving inflammatory processes." (PMID 28962574, 2017).
SDC4 also shares sentences with these, for which no sentence is quoted: thyroid cancer (4 papers); acute myocardial infarction (3); age (2); coronary artery disease (2); Hyperglycemia (2); hypertrophy (2); infarction (2); Insulin resistance (2); mesothelioma (2); prostate carcinoma (2); acute kidney injury (1); acute myocarditis (1); acute respiratory distress syndrome (1); allergic asthma (1); amyotrophic lateral sclerosis (1); angina (1); ankylosing spondylitis (1); choroidal neovascularization (1); chronic obstructive pulmonary disease (1); colitis (1); corneal infection (1); craniorachischisis (1); embryonal carcinoma (1); essential hypertension (1); glaucoma (1); glucocorticoid deficiency (1); head and neck carcinoma (1); HELLP syndrome (1); Hepatitis (1); hepatitis B virus infection (1).
A further 24 diseases each share a sentence with SDC4 in 1 paper.